BRCA1 (BRCA1 DNA repair associated)
Diseases named in the same sentence as BRCA1 in open-access papers (continued):
Sharing a sentence is not in itself a finding about the gene and the disease.
Anxiety (continued). "The aim of this study was to obtain insights into the relationship between coping self-efficacy and psychological morbidity in newly found BRCA1/2 PV carriers, such as clinical anxiety, depression, and post-traumatic stress." (PMID 36767056, 2023). "The high rates of clinical anxiety support the notion for low-threshold psycho-oncological support, which should routinely be offered to newly diagnosed BRCA1/2 PV carriers." (PMID 36767056, 2023). "Altered BRCA1 repair with rmTBI resulted in altered anxiety-related behaviours in males and females using elevated zero maze and contextual fear conditioning." (PMID 37638313, 2023). "Although VUS in any gene complicates decision-making for clinicians and is a source of anxiety for patients, VUS in high penetrance cancer causing genes like BRCA1/2 is especially problematic." (PMID 36200007, 2022). "High persistent anxiety levels in women carrying PVs in BRCA1/2 should be taken into account when developing concepts for counseling these women." (PMID 36536421, 2022). "To date, this is the first study to analyze anxiety and depression considering several COVID-19 predictors among BRCA1/2 -positive women." (PMID 34401875, 2021). "Among BRCA1/2-positive women residing in the US, the current study analyzed relationships between experiencing COVID-19-related instances and odds of reporting anxiety and depression overall and stratified by sociodemographic factors." (PMID 34969949, 2021). "Overall, psychological and psychoeducational interventions for women with a BRCA1 or BRCA2 mutation are well-received by participants, and some have been shown to reduce distress, depression, and anxiety." (PMID 33804884, 2021). "These were based on surveys/interviews evaluating the impact of genetic testing for BRCA1/2 that used various patient-reported outcome measures (e.g., the Cancer Worry Scale, Hospital Anxiety and Depression Scale) at different time points." (PMID 34638366, 2021). "This extended version captures a broader spectrum of concerns, offering greater sensitivity in identifying and understanding cancer-related anxiety, particularly among BRCA1/2 carriers, who are a special population due to their unique genetic predisposition and specific psychological needs." (PMID 40390061, 2025). "In the case of the GHR tests, using the example of tests for BRCA1, a false-positive test could lead a consumer to experience anxiety or depression, or to have a preventive mastectomy or oophorectomy, which are invasive and serious procedures." (PMID 41450770, 2025). "Due to this, undergoing testing for a BRCA1/2 PV and finding out about a confirmed PV status may induce a variety of emotions in cancer-unaffected women, including anxiety, cancer worry, and even depressive symptoms." (PMID 36767056, 2023). "While WT mice with rmTBI exhibited minimal changes in behaviour, mislocalization of BRCA1, and activation of the DDR and senescence-associated pathways, HET mice with rmTBI exhibited changes in anxiety-related behaviours and distinct molecular phenotypes between males and females." (PMID 37638313, 2023). "Anxiety levels at baseline (T0) may correlate with the perceived likelihood of carrying a PV, which may differ in women from families with PVs in BRCA1/2." (PMID 36536421, 2022). "It was found that short-term potential anxiety existed in BRCA1/2 mutation-positive or negative patients, while the long-term effect was limited." (PMID 27428375, 2016). "In view of the highly invasive interventions recommended in patients with pathogenic BRCA1 or BRCA2 variants, VOUS in these genes are particularly challenging and we hope our efforts will help alleviate the anxiety and confusion associated with at least some of these variants." (PMID 27884173, 2016).
Anxiety (continued). "The key question is if the small reduction in depression and anxiety potentially associated with RRM justifies the possible small decline in quality of life, body image satisfaction, and sexual well-being for the individual carrier of a P/LP variant in BRCA1/2 genes." (PMID 40445415, 2025). "Thus, altered DNA repair, elicited here by a BRCA1 heterozygous knockout, may work in a similar manner to differentially alter anxiety-related behaviours in both males and females with rmTBI." (PMID 37638313, 2023). "Thus, prophylactic surgery of the reproductive organs not only decreases the mortality rate among patients with the BRCA1/BRCA2 mutations but also has a positive emotional effect, as it eliminates the patient’s constant anxiety about their own future, health, and, in particular, life." (PMID 31818005, 2019). "In fact, it is possible that their anxiety could be related to the cancer treatments/fear of loss for their loved ones, rather than being related to genetic testing for BRCA1/2 mutations." (PMID 29026449, 2017). "The key question is whether the small reduction in depression and anxiety potentially associated with RRM justifies the possible small decline in quality of life, body image satisfaction, and sexual well-being for the individual carrier of a P/LP variant in BRCA1/2." (PMID 40445415, 2025). "However, even individuals who were BRCA1/2-positive and had HADS Anxiety scores < 8, 22% (4/18) had MICRA Total scores higher than 31 points." (PMID 40900191, 2025). "Those who were BRCA1/2-positive and had a HADS anxiety score ≥ 8 exceeded 31 points (8/9, 89%)." (PMID 40900191, 2025). "Further research indicates that signs of a negative self-concept in women with BRCA1/2 PVs, such as feelings of stigma, can have negative effects by increasing anxiety as well as BC-specific and general distress." (PMID 39875875, 2025). "In a recent prospective study of 98 BRCA1/2 carriers in Germany, baseline anxiety levels were higher in women opting for RRM but decreased after surgery, whereas women opting for enhanced surveillance tended to have increased levels of anxiety over time." (PMID 38248108, 2024).
bladder cancer (32 papers, 2010 to 2026). "The 1028 bladder cancer cases and 4000 controls were successfully genotyped for the BRCA1 (5328 insC, C61G, 4153 delA) mutations." (PMID 35395863, 2022). "Of the missense variants examined in fishing cat gene orthologs for human bladder cancer risk genes, DNA damage repair pathway genes BRCA1/2, CHEK2, and ATM all showed higher missense variant prevalence in the cohort; however, only BRCA2 showed a skewed distribution in TCC over healthy cats." (PMID 38580653, 2024). "Intronic BRCA1 mutation c.5050-104 C >T was reported among the four investigated bladder cancer patients, and three somatic mutations were reported as follows: two of them were found to be benign rs1064793056 and rs28897679 on the Clinivar database and one nonsense pathogenic variant rs80357006." (PMID 34152511, 2021). "All the examined bladder cancer cell lines were BRCA1 and BRCA2 wild-type, and therefore the observed viability is not influenced by BRCA mutational status." (PMID 40025053, 2025). "According to an analysis of prognostic data from 57 patients with locally advanced bladder cancer, patients with elevated BRCA1 expression were less likely to benefit from cisplatin-based therapy." (PMID 39113697, 2024). "In contrast, in bladder cancer, upregulation of BRCA1 was able to resist oxidative stress, thereby promoting bladder cancer cell growth." (PMID 35035831, 2022). "BRCA1 has been reported to play an oncogenic role in bladder cancer, with significantly lower expression levels in cancer tissues than in normal tissues, and overexpression of BRCA1 reduced cell proliferation, migration, and colony-forming ability." (PMID 35035831, 2022). "A similar result was found in bladder cancer where a significant pathologic response to neoadjuvant cisplatin-based chemotherapy was attained in 66% of patients with low/intermediate BRCA1 levels compared with 22% of patients with high BRCA1 levels (P = 0.01)." (PMID 22400017, 2012). "Notably, TCGA analysis also found an inverse correlation in CISAL and BRCA1 expression in bladder carcinoma." (PMID 32000125, 2020). "Along the same lines, in a retrospective study of locally advanced bladder cancer patients treated with cisplatin-based chemotherapy, those with low or intermediate levels of BRCA1 mRNA attained significantly better response, disease-free survival and OS than those with high levels." (PMID 20209131, 2010). "In bladder carcinoma therapy, radiation is commonly used in conjunction with cisplatin, a DNA damaging agent which may further potentiate creation of double strand lesions that would be accumulating in cancers with epigenetic BRCA1 neutralization." (PMID 35323317, 2022). "Also, the relation between BRCA1 mRNA and cisplatin-based neoadjuvant chemotherapy was studied and emphasized that the detection of BRCA1 mRNA expression could estimate both the sensitivity to chemotherapy and prognosis among patients with bladder cancer." (PMID 34152511, 2021). "Our results showed that downregulation of RNF8 impaired the recruitment of BRCA1 and RAP80 to DNA damage sites in bladder cancer cells." (PMID 26788910, 2016). "The gene expressions of BRCA1, MDR1, and ERCC1 were reported to be useful as markers to predict the efficacy of chemotherapy for bladder cancer patients." (PMID 24354468, 2013).
bladder cancer (continued). "BRCA1 is a crucial component of the BRCC3 complex, leading to our conjecture that USP15 may activate the NF-κB pathway by deubiquitinating BRCC3, thereby augmenting its expression and ultimately influencing bladder cancer progression." (PMID 38656882, 2024). "Thus, Use of ERCC1, MDR1, BRCA1, and Snail in combination with DYRK2 may further improve the accuracy of predicting survival in bladder cancer patients treated with neoadjuvant chemotherapy." (PMID 26087959, 2015).
Li-Fraumeni syndrome (32 papers, 2011 to 2026). "Currently, most of the recommendations for genetic testing for non-BRCA1/2 genes are based on specific cancer syndromes with well-studied clinical features, such as the Li-Fraumeni syndrome and Cowden syndrome." (PMID 32318955, 2020).
lung adenocarcinoma (32 papers, 2009 to 2026). A carcinoma that arises from the lung and is characterized by the presence of malignant glandular epithelial cells. "Lung adenocarcinoma (LUAD) patients with elevated breast cancer susceptibility gene 1 (BRCA1) expression had markedly worse overall survival and progression‐free survival compared to those with reduced BRCA1 levels." (PMID 38090061, 2023). "Our study results suggest that BRCA1 overexpression was associated with poor prognosis in lung adenocarcinoma." (PMID 32607285, 2020). "The pan-cancer analysis showed that the level of BRCA1 was higher in most tumors compared to normal tissues, such as lung adenocarcinoma, bladder urothelial carcinoma, bile duct cancer, etc.." (PMID 38224491, 2024). "BAP1 is a tumor suppressor gene that contains binding domain for BRCA1 and BARD1; germline mutations predispose patients to a variety of cancers including uveal and cutaneous melanoma, mesothelioma, lung adenocarcinoma, meningioma, and renal cell carcinoma." (PMID 38700789, 2024). "We did not observe an association between hormone receptor status with BRCA1, BRCA2 or EGFR mutation status in lung adenocarcinoma patients." (PMID 37461096, 2023). "Previous studies show that low BRCA1 expression is correlated with poor outcome in LUSC patients but, in contrast, is associated with a better response to platinum-based chemotherapy in lung adenocarcinoma (LUAD) patients." (PMID 34068585, 2021). "Another major finding of our study is that BRCA1 is a predictor in patients with lung adenocarcinoma." (PMID 32607285, 2020). "Overall, these findings suggest that BRCA1 plays a key role in the immunomodulatory pathway of lung adenocarcinoma." (PMID 32607285, 2020). "Taken together, these data confirmed that MYBL2 High lung adenocarcinomas exhibited a novel genomic instability phenotype with inefficient HR in the presence of highly expressed, wildtype BRCA1/2." (PMID 33489883, 2020). "BRCA1/2, the genes responsible for double-strand break repairing, had a significantly lower expression due to its promoter hypermethylation in lung adenocarcinoma, potentially mediating genetic instability in lung tumorigenesis." (PMID 31703574, 2019). "Further, we identified BRCA1 as an endogenous ERβ-interacting protein in lung adenocarcinoma cell lines and in human lung adenocarcinomas." (PMID 21951318, 2011). "However, another study that compared the rate of prevalence of BRCA1 and BRCA2 PGVs in patients with lung adenocarcinoma with ATM PGVs reported a higher prevalence of BRCA1 and BRCA2 PGVs." (PMID 38539485, 2024). "Interestingly, the expression of BRCA1, BRCA2, BLM and RAD51 was significantly associated with poor prognosis in lung adenocarcinoma." (PMID 37298484, 2023). "In a gene expression study of 10 ‘signature’ genes in early lung adenocarcinoma, a two-gene signature, comprising only ERBB3 and BRCA1 expression was an independent risk factor in predicting survival, improving the discriminatory power of conventional classification systems." (PMID 34274969, 2021). "In particular, our results indicate that BRCA1 was mainly involved in cell cycle and DNA damage responses in lung adenocarcinoma, which might produce new antigens and enhance immune responses." (PMID 32607285, 2020). "However, these different mutant forms of hub genes were involved in different signaling pathways influencing the development of lung adenocarcinoma; for example, BRCA1 was mainly involved in the cell cycle and DNA damage response pathways." (PMID 32607285, 2020). "Notably, survival analysis revealed BRCA1, mainly involved in cell cycle and DNA damage responses, to be a novel prognostic indicator in lung adenocarcinoma." (PMID 32607285, 2020). "Although several studies have demonstrated the role of BRCA1 in NSCLC, the prognostic value and possible mechanism of BRCA1 in lung adenocarcinoma remain unclear." (PMID 32607285, 2020).
lung adenocarcinoma (continued). "In fact, combination of inhibition of CDK1 and PARP in BRCA-proficient cells resulted in reduced colony formation, tumor xenograft growth inhibition and tumor regression with prolonged survival in a mouse lung adenocarcinoma model, despite BRCA1 downregulation." (PMID 30002440, 2018). "The HRR genes BRCA1/2 are key regulators of DNA repair, yet their impact on the tumor microenvironment (TME) in lung adenocarcinoma (LUAD) remains unclear." (PMID 42189716, 2026). "However, although the expression levels of BRCA1 and RFC4 were higher in lung adenocarcinoma tissues than in adjacent normal tissues, the differences were not significant." (PMID 32607285, 2020). "BRCA1 interacted with ERβ in A549 cell lines and in human lung adenocarcinoma tumors, but not normal lung tissue." (PMID 21951318, 2011). "However, previous findings on the prognostic value of BRCA1 for NSCLC have been inconsistent or conflicting, which may be attributed to the small number of patients from a single center or disparity in the ratio of patients with lung adenocarcinoma (LUAD) versus squamous cell carcinoma (LUSC)." (PMID 38090061, 2023).
lymph node metastasis (32 papers, 2011 to 2025). "Our findings show that early age at diagnosis, lymph node metastasis, and positive family history of any cancer are independent predictors BRCA1/2 mutations, which have important clinical implications for screening and early diagnosis in our population." (PMID 34206661, 2021). "Furthermore, BRCA1 methylation was statistically associated with lymph node metastasis, histological grade 3, ER(-), PR(-), triple-negative phenotype, and decreased or lack levels of BRCA1 protein expression." (PMID 26643130, 2015). "Multivariate analysis which incorporated variables of patients' age, tumor size, grade, and lymph node metastasis revealed that BRCA1 promoter methylation was associated with overall survival (p = 0.27; hazard ratio, 16.38) and disease-free survival (p = 0.003; hazard ratio, 12.19)." (PMID 23405268, 2013). "A significantly higher proportion of non-BRCA1/2 carriers (40.0%) had axillary lymph node metastases (stages II–III) compared with both BRCA1/2 carriers (14.3%) and non-carriers (12.2%, p = 0.023)." (PMID 37791908, 2023). "The patient with BRCA1 p.Leu481fs was diagnosed with BC at the age of > 45 years but had lymph node metastasis and was in stage III." (PMID 34570441, 2021). "The patients with BRCA1 p.Ile1824fs and p.Leu1306fs were diagnosed with BC at the age of ≤ 45 years and had lymph node metastases." (PMID 34570441, 2021). "Positive lymph node metastasis was more frequently observed in BRCA1/2 carriers (76% vs. 53%, p = 0.03)." (PMID 34206661, 2021). "The factors included in the multivariate analysis of OS and RFS were age, tumor stage, lymph node metastasis, presence of ascites, bilaterality of the tumor, histologic grade, BRCA1 expression, and DBC1 expression." (PMID 25823848, 2015). "In Cox proportional hazards analysis, BRCA1 promoter methylation status was analyzed with tumor size, lymph node metastasis, histological grade, and age for their impact on OS and DFS." (PMID 23405268, 2013). "Among the significant methylated genes, APC, BMP6, BRCA1 and P16 represented higher methylation proportions in matched lymph node metastasis compared to those of the normal tissue (P < 0.05 and P < 0.01, P < 0.0001, P < 0.05; respectively)." (PMID 22695536, 2012). "Lymph node metastasis was observed in 78.9% and 50.8% of patients with or without BRCA1/2 mutations, respectively." (PMID 36358026, 2023). "The BRCA1 p.Asp1362fs mutation carriers were ≥ 45 years of age, in stage I, and had no lymph node metastasis." (PMID 34570441, 2021). "In addition, a panel with BRCA1 mutation, BRCA2 mutation, and five serum markers (AFP, CA125, CA19‐9, CA242 and HE4) showed a good performance for identifying patients with lymph node metastasis (AUC = 0.843, Sensitivity = 0.600, Specificity = 0.902)." (PMID 30972954, 2019). "Our results also indicated that BRCA1/2 mutation carriers had more lymph node metastasis than nonmutation carriers, especially in BRCA1 mutation carriers." (PMID 30972954, 2019). "The contribution of aberrant methylation alterations of BMP6, BRCA1 and P16 genes in lymph node metastasis might provide a further clue to establish useful biomarkers for screening metastasis." (PMID 22695536, 2012).